TRAF3 (TNF receptor associated factor 3)
Diseases named in the same sentence as TRAF3 in open-access papers (continued):
Sharing a sentence is not in itself a finding about the gene and the disease.
lung adenocarcinoma (4 papers, 2020 to 2023). A carcinoma that arises from the lung and is characterized by the presence of malignant glandular epithelial cells. "The protein expression level of TRAF3 was markedly upregulated in lung adenocarcinoma cells compared with that in normal lung epithelial cells (P<0.01)." (PMID 37798663, 2023). "We observed that silencing TRAF3 significantly decreased the sensitivity of lung adenocarcinoma cells to PTX, indicating that TRAF3 and PTX have synergistic antitumor effect." (PMID 37798663, 2023). "It is consistent with the previous conclusion that TRAF3 plays a tumor inhibitory role in lung adenocarcinoma." (PMID 37798663, 2023). "As evidenced by these results, mediating TRAF3 is a promising treatment choice in lung adenocarcinoma." (PMID 37798663, 2023). "In conclusion, inhibiting of TRAF3 not only promoted the proliferation and migration of lung adenocarcinoma, but weakened the reactive sensitivity of the cells to paclitaxel." (PMID 37798663, 2023). "Kaplan-Meier Plotter database was utilized to explore the effect of TRAF3 on the clinical prognosis of lung adenocarcinoma patients." (PMID 37798663, 2023). "TIMER2.0 database and western blot were applied to detect the expression of TRAF3 in lung adenocarcinoma tissue." (PMID 37798663, 2023). "Our findings suggest that TRAF3 inhibition can facilitate the proliferation and migration of lung adenocarcinoma cells, and reduce the sensitivity of LUAD cells to paclitaxel, partly by mediating the caspase-1-dependent pyroptosis." (PMID 37798663, 2023). "In the present study, we revealed that inhibition of TRAF3 promoted the proliferation and migration of lung adenocarcinoma cells." (PMID 37798663, 2023). "Nevertheless, Kaplan-Meier Plotter database showed that patients with TRAF3 hyperexpression in lung adenocarcinoma had significantly longer overall survival and progression-free survival compared to those with lower expression." (PMID 37798663, 2023). "Next, we used the Kaplan-Meier Plotter to explore the effect of TRAF3 on the clinical prognosis of lung adenocarcinoma patients." (PMID 37798663, 2023). "Based on the existing results, we preliminarily concluded that TRAF3 plays a tumor inhibitory role in lung adenocarcinoma, in part by mediating caspase-1-dependent pyroptosis." (PMID 37798663, 2023). "As shown through a series of in vitro and in vivo experiments, miR-1307-5p promotes the proliferation of lung adenocarcinoma, and miR-1307-5p targeting TRAF3 upregulates the MAPK/NF-κB pathway." (PMID 33061854, 2020). "Consistent with previous in vitro studies, miR-1307-5p promotes proliferation of lung adenocarcinoma cells in vivo and binds to TRAF3." (PMID 33061854, 2020). "Compared with the control group and the blank group, lung adenocarcinoma cells in the mimic group showed lower expression of cytoplasmic TRAF3 while p65 fluorescence was enhanced and expressed in both the cytoplasm and the nucleus." (PMID 33061854, 2020). "It suggests that TRAF3 may inhibit the development of lung adenocarcinoma by regulating the caspase-1-dependent pyroptosis signaling." (PMID 37798663, 2023). "The effect of overexpression of TRAF3 on lung adenocarcinoma needs to be clarified." (PMID 37798663, 2023). "TRAF3 was highly expressed in lung adenocarcinoma tissues and cell lines." (PMID 37798663, 2023). "Therefore, our group conducted some preliminary studies on the role of TRAF3 in lung adenocarcinoma." (PMID 37798663, 2023). "Inhibition of TRAF3 also weakened the sensitivity of lung adenocarcinoma cells to paclitaxel." (PMID 37798663, 2023). "Therefore, the miR-1307-5p/TRAF3/NF-κB/MAPK axis may be a new target for the treatment of human lung adenocarcinoma and may be further identified as a potential prognostic factor in the future." (PMID 33061854, 2020). "To verify the role of pyroptosis in lung adenocarcinoma and the involvement of TRAF3 in LUAD cells pyroptosis, we first queried the correlation between TRAF3 and pyroptosis-related genes." (PMID 37798663, 2023).
lung adenocarcinoma (continued). "With the aid of TIMER2.0 database, we found that TRAF3 was positively correlated with the expression of ASC (R = 0.09, P<0.05), caspase-1 (R = 0.32, P<0.01) and IL-1β (R = 0.37, P<0.01) in lung adenocarcinoma." (PMID 37798663, 2023). "However, the effect and mechanism of TRAF3 on lung adenocarcinoma (LUAD) are still unknown." (PMID 37798663, 2023). "Xinyue Du (2020) reported the role of miR-1307-5p in proliferation and invasion by targeting TRAF3 and activating the NF-κB/MAPK pathway in lung adenocarcinoma." (PMID 36142544, 2022). "We demonstrated that miR-1307-5p targets TRAF3 and activates NF-κB/MAPK pathway to promote the proliferation of lung adenocarcinoma." (PMID 33061854, 2020). "In conclusion, miR-1307-5p targets TRAF3 and activates the NF-κB/MAPK pathway to promote proliferation in lung adenocarcinoma." (PMID 33061854, 2020). "We first analyzed the correlation between TRAF3 and pyroptosis-related genes through TIMER2.0 database, the results showed that TRAF3 was positively correlated with the expression of ASC, caspase-1 and IL-1β in lung adenocarcinoma." (PMID 37798663, 2023). "TRAF3 has been reported to promote the proliferation of lung adenocarcinoma, but has not been well studied in liver cancer." (PMID 35937592, 2022).
ovarian carcinoma (4 papers, 2013 to 2023). A malignant neoplasm originating from the surface ovarian epithelium. "recently reported that TRAF3 interacts with the mitochondrial fusion protein mitofusin-1 (MFN1) in ovarian cancer cells, which is enhanced upon TLR4 signaling induced by Selene nanoparticles." (PMID 36776285, 2023).
rheumatoid arthritis (4 papers, 2018 to 2025). A chronic, systemic autoimmune disorder characterized by inflammation in the synovial membranes and articular surfaces. "In conclusion, circ-CBLB promotes macrophage polarization toward the M1 phenotype by regulating the TLR3/TRAF3 signaling pathway, thereby exacerbating the inflammatory response in rheumatoid arthritis." (PMID 40746530, 2025). "Hydroxychloroquine (HCQ), which is used to treat rheumatoid arthritis, prevents the lysosomal degradation of TNF receptor-associated factor 3 (TRAF3), an NF-κB adaptor protein that limits bone resorption and maintains bone formation." (PMID 38746138, 2024). "Chloroquine and hydroxychloroquine, anti-inflammatory drugs used to treat rheumatoid arthritis, prevent TRAF3 degradation in osteoclast precursors and inhibit osteoclast formation in vitro." (PMID 30323820, 2018). "TRAF3 also limits osteoclast formation induced by TNF, which mediates inflammation and joint destruction in inflammatory diseases, including rheumatoid arthritis." (PMID 30323820, 2018).
Sepsis (4 papers, 2016 to 2023). Sepsis is defined as life-threatening organ dysfunction caused by a dysregulated host response to infection. "Our findings are also in line with Wen's results, which displayed that the expression of TRAF3 in the state of ET is upregulated in Kupffer cells to improve the prognosis of sepsis." (PMID 37506157, 2023). "SGT1 and TRAF3 decreased consistently in septic patients, which serves as extra proof that they can be candidate therapeutic target molecules in sepsis." (PMID 35720321, 2022). "Flow cytometry analysis further revealed that downstream effectors of TLR9, including IRF3, MyD88, and TRAF3, were elevated in all of the sepsis patients compared with the normal donors, and was correlated with improved prognosis in patients with sepsis." (PMID 31534550, 2019). "In sepsis, whether HSF1 can participate in the activation of the NLRP3 inflammasome by regulating the expression of TRAF3 is still unclear." (PMID 35720321, 2022).
asthma (3 papers, 2022 to 2026). "We link discovered eQTLs to associations identified in pediatric and adult asthma and atopy traits, nominating 78 eGenes like TRAF3, ZBTB10 and JAZF1 in disease relevant cell types." (PMID 41889912, 2026). "The SNP rs12436181 (near genes TRAF3, AMN) was associated with childhood-onset asthma, eczema, body size at age 10 years, and weight in the Open Targets Genetics20." (PMID 36253437, 2022).
B-cell neoplasm (3 papers, 2015 to 2023). A group of heterogeneous lymphoid tumors generally expressing one or more B-cell antigens or representing malignant transformations of B-lymphocytes. "Previous studies showed that TRAF3 overexpression renders B cells hyperreactive to antigens and TLR agonists, while TRAF3 deficiency has been implicated in developing a variety of B cell neoplasms." (PMID 36845015, 2023). "Previous studies showed that TRAF3 overexpression renders B cells hyper-reactive to antigens and Toll-like receptor (TLR) agonists, while TRAF3 deficiency has been implicated in the development of a variety of B cell neoplasms." (PMID 30687320, 2018). "Together, our in vitro and in vivo data provided the preclinical evidence for the therapeutic potential of oridonin in the treatment of B cell neoplasms with TRAF3 deletions or inactivating mutations." (PMID 25960828, 2015). "We have tested several drugs targeting NF-κB2 and PKCδ, and found that both oridonin and AD198 exhibit potent anti-tumor activities on B cell neoplasms with TRAF3 deletions or inactivating mutations." (PMID 25960828, 2015). "In contrast, the B cell neoplasms developed by the B cell-specific Traf3-deficient mice were consistent with SBL/CLL and MZL, with over 86% of the expanded cloned having non-mutated VHDJH regions (applying the 97.5% identity to the germ line criteria that we have used in our analyses)." (PMID 30687320, 2018). "However, further studies (using genetic means or more specific PKCδ activators) are required to establish the possibility of activating PKCδ nuclear translocation as a therapeutic avenue for B cell neoplasms with TRAF3 deletions or inactivating mutations." (PMID 25960828, 2015). "FACS and immunohistochemical analyses show that different types of mature B cell neoplasms arise in TRAF3/BCL2 double-transgenic (tg) mice, all of which are characterized by the loss of surface IgM and IgD expression." (PMID 30687320, 2018). "As shown in this report, lymphoid-specific TRAF3/BCL2 double-tg mice develop B cell neoplasms, mostly DLBCL and plasma cell neoplasia, with high incidence (approximately 80% of the mice)." (PMID 30687320, 2018). "For these experiments we used lymphocytes from mice representing three of the most characteristic of the B cell neoplasms developed by the TRAF3/BCL2 double-tg mice." (PMID 30687320, 2018). "Our findings suggest that oridonin or closely related NF-κB2 inhibitors should be considered as new candidates for the treatment of B cell neoplasms characterized by genetic/epigenetic inactivation of TRAF3 or TRAF3-dependent signaling pathways." (PMID 25960828, 2015). "Collectively, our findings indicate that restoration of TRAF3 downstream signaling pathways represents an important line of new therapeutic avenues for B cell neoplasms." (PMID 25960828, 2015). "In this context, we have been investigating TRAF3 signaling mechanisms in B cells, and are developing new therapeutic strategies to target TRAF3 downstream signaling pathways in B cell neoplasms." (PMID 25960828, 2015). "Our findings thus support further clinical studies of AD 198 as an anti-cancer agent for B cell neoplasms involving TRAF3 inactivation or Myc up-regulation." (PMID 25960828, 2015). "TRAF3/BCL2 +/+ B cell neoplasms can be transferred to and survive in immunodeficient mice." (PMID 30687320, 2018). "Since our new proteomic data identified PARP1 and PHB2/PHB1 as two signaling hubs of the novel oncoprotein MCC in human MM cells, we are currently testing the therapeutic efficacy of PARP1 inhibitors and PHB ligands in B cell neoplasms with TRAF3 inactivation or aberrant MCC expression." (PMID 25960828, 2015). "Given the preclinical evidence that both PARP1 and PHB2/PHB1 are excellent therapeutic targets in human cancers, our findings also implicate potential applications of PARP inhibitors and PHB ligands in the treatment of B cell neoplasms involving TRAF3 inactivation or aberrant MCC expression." (PMID 25960828, 2015).
B-cell neoplasm (continued). "The latest report showed that transgenic mice overexpressing TRAF3 in B cells develop with high-incidence severe lymphadenopathy, splenomegaly, and lymphoid infiltrations into tissues and organs, which is the result of the growth of monoclonal and oligoclonal B cell neoplasms." (PMID 36845015, 2023). "However, whether SOX5 can serve as a therapeutic target in human B cell neoplasms involving TRAF3 inactivation or aberrant SOX5 expression awaits further investigation." (PMID 25960828, 2015). "Although TRAF3 deletions or mutations exist in human patients with B cell neoplasms, it is not known whether TRAF3 inactivation is the primary or secondary oncogenic event in human samples." (PMID 25960828, 2015). "Together, our results indicate that c-Myc suppression is a major contributing factor to the anti-tumor effects of AD 198 in both TRAF3−/− and TRAF3-sufficient B cell neoplasms." (PMID 25960828, 2015). "Altogether, these results indicate that TRAF3, perhaps by promoting exacerbated B cell responses to certain antigens, and BCL2, presumably by supporting survival of these clones, cooperate to induce mature B cell neoplasms in transgenic mice." (PMID 30687320, 2018).
cardiac hypertrophy (3 papers, 2016 to 2021). "In the heart, TRAF3 mediates GPCR (G-coupled protein receptor)-stimulated cardiac hypertrophy through activation of TBK1-AKT-mTOR signaling, which results in increased protein synthesis that contributes to the hypertrophic response." (PMID 34440839, 2021). "In addition, knockdown of TBK1 almost prevented the cardiac hypertrophy by TRAF3 overexpression in response to Ang II." (PMID 30186311, 2018). "Whereas, transgenic mice overexpressing TRAF3 showed an increase in cardiac hypertrophy after 4 weeks as indicated by significant increase in cardiomyocyte size and fibrosis as well as higher HW/BW, HW/TL, and LW/BW ratios and increased mRNA level of cardiac fetal genes (ANP, BNP, and β-MHC)." (PMID 30186311, 2018).
colon cancer (3 papers, 2018 to 2024). "In line with the in vivo data, mutations and deletions of TRAF3 are detected in 2.3% (10/439) of human colon cancers (TCGA, PanCancer Atlas)." (PMID 30294322, 2018). "Alterations of TRAF2 and TRAF3 in colon cancer (CC) along with their regional difference and microsatellite instability (MSI) are largely unknown." (PMID 34257589, 2021). "Colon cancer (CC) cell lines show TRAF2 and TRAF3 expressions in 30–60% of the cases, while they are not or weakly expressed in normal colon tissues." (PMID 34257589, 2021).
Glucose intolerance (3 papers, 2016 to 2024). Glucose intolerance (GI) can be defined as dysglycemia that comprises both prediabetes and diabetes. "Myeloid cell-specific deletion of TRAF3 also protects against HFD-induced glucose intolerance." (PMID 35807520, 2022). "Interestingly, hepatic deletion of TRAF3 protects against HFD-induced glucose intolerance by increasing insulin sensitivity." (PMID 35807520, 2022).
head and neck cancer (3 papers, 2023 to 2025). A primary or metastatic malignant neoplasm affecting the head and neck. "Importantly, activation of NF-κB via depletion of TRAF3 or CYLD resulted in elevated radiosensitivity of HPV+ head and neck cancer cells." (PMID 37523561, 2023). "Indeed, we found that experimental TRAF3 and CYLD inactivation was sufficient to strikingly sensitize HPV+ head and neck cancer cells to radiation, as well as promote increased expression of well-known NF-κB targets and sky blue (NF-κB) module genes." (PMID 37523561, 2023).
Hepatic steatosis (3 papers, 2016 to 2022). Steatosis is a term used to denote lipid accumulation within hepatocytes. "The potent regulatory activity of TRAF3 in hepatic steatosis and associated pathologies prompted us to explore the underlying mechanisms." (PMID 26882989, 2016). "On the contrary, the adverse role of TRAF3 in liver steatosis has also been unraveled via stimulation of TAK1 ubiquitination and nullification of protein stability." (PMID 35260558, 2022). "We identify positive regulatory role of hepatocyte TRAF3 in hepatic steatosis, insulin resistance and inflammatory response." (PMID 26882989, 2016). "The upregulated expression of TRAF3 in livers with hepatic steatosis suggests a potential involvement of TRAF3 in this pathological condition." (PMID 26882989, 2016). "In this study, hepatic TRAF3 expression can be elevated by HFD and in turn promote all of the three pathologies, suggesting a therapeutic promising of TRAF3 for hepatic steatosis-related metabolic diseases." (PMID 26882989, 2016). "In conclusion, hepatocyte TRAF3 promotes HFD-induced or genetic hepatic steatosis in a TAK1-dependent manner." (PMID 26882989, 2016). "The detrimental effects of TRAF3 on hepatic steatosis and related pathologies are confirmed in ob/ob mice." (PMID 26882989, 2016). "In contrast to amelioration of hepatic steatosis in TRAF3-LKO mice, the liver-specific overexpression of TRAF3 caused an opposite effect on hepatic lipid accumulation and liver function." (PMID 26882989, 2016). "Collectively, these findings show that hepatocyte TRAF3 exacerbates HFD-induced hepatic steatosis and the related inflammatory responses." (PMID 26882989, 2016). "Consistent with the in vivo investigations into HFD-induced hepatic steatosis, TRAF3's function in exacerbating lipid accumulation was found in L-02 hepatocyte cell line treated with palmitate as shown by oil red O staining." (PMID 26882989, 2016). "Here, the authors show that TRAF3 is upregulated in the liver in non-alcoholic fatty liver disease, promoting insulin resistance, inflammation and hepatic steatosis via its interaction with the kinase TAK1." (PMID 26882989, 2016). "Once the proposed interaction between TRAF3 and TAK1 has been disrupted, the regulatory function of TRAF3 on HFD-induced hepatic steatosis was almost completely neutralized." (PMID 26882989, 2016). "Therefore, the deleterious effects of TRAF3 on hepatic steatosis are largely dependent on the activation of TAK1." (PMID 26882989, 2016). "Thus, the activation of TAK1 is indispensable during TRAF3-regulated hepatic steatosis and related metabolic disorder." (PMID 26882989, 2016). "In addition to the excess energy intake model, an ob/ob (leptin-deficient) mouse model was employed in this study to evaluate the role of hepatic TRAF3 in genetically induced hepatic steatosis." (PMID 26882989, 2016). "Therefore, the TRAF3–TAK1 interaction and the subsequent TAK1 ubiquitination is required for and contributes to the exacerbation of hepatic steatosis and insulin resistance mediated by hepatocyte TRAF3." (PMID 26882989, 2016). "Next, to evaluate whether TRAF3–TAK1 interaction is required for the regulatory function of TRAF3 on hepatic steatosis, an adenovirus harbouring TRAF3 with a mutant 267–376 aa domain (AdTRAF3-M) was constructed and injected into WT mice in parallel with AdTRAF3 at 20 weeks of HFD administration." (PMID 26882989, 2016). "However, whether TRAF3 in hepatocytes can mediate hepatic steatosis remains unknown." (PMID 26882989, 2016). "Furthermore, TRAF3 expression levels were examined in the liver, muscle and fat of wild-type (WT) mice subjected to an HFD-induced hepatic steatosis." (PMID 26882989, 2016).